CD4 (CD4 molecule)
Diseases named in the same sentence as CD4 in open-access papers (continued):
Sharing a sentence is not in itself a finding about the gene and the disease.
infection (continued). "A significantly increased proportion of IFNγ-releasing CD4+ T cells was detected when splenocytes were co-cultured with lung cells from the 84-day infection with the treatment of isoniazid group relative to the untreated control group." (PMID 32411131, 2020). "At days 2.5, 5, 8, and 30 after infection, we sorted the transferred SM CD4 T cells from the spleens of chimeric recipients and analyzed their EZH2 expression levels by confocal microscopy." (PMID 32999031, 2020). "In rhesus macaques challenged with simian immunodeficiency virus, dendritic cell (DC) mediated recruitment of CD4+ T cells to the FGT was critical for infection." (PMID 32615983, 2020). "The L. donovani infection in BALB/c mice promotes IL-27 expression by splenic CD8α+ and CD4+ DCs on days 1, 14, and 28 post-infection." (PMID 32849534, 2020). "On the other hand, coupling to the CD4-targeting mAb ibalizumab was shown to efficiently concentrate HIV-1 broadly neutralizing VHHs at the site of infection." (PMID 33322697, 2020). "These latently infected cells are extremely rare (typically <1 in 106 CD4 T cells), making their direct observation and analysis difficult, yet, sporadic reactivation of these cells reseeds infection, leading to rebound during treatment interruption." (PMID 33202596, 2020). "Nevertheless, the infected fish at 15°C showed overexpression of STAT1, MHCII, CD4, IgT, and IgM transcripts, suggesting that the infection triggered a CD4+ T-cells response and a humoral response." (PMID 32695119, 2020). "Within individuals, activated CD4+ T cells following infection were significantly more frequent in BAL than blood (mean, 4.73% ± SEM 1.97 vs. 1.17% ± SEM 0.137; P = 0.0273)." (PMID 31815739, 2020). "For example, in human immunodeficiency virus (HIV), despite its impressive genetic diversity, which is particularly high at the level of its envelope proteins, infection remains essentially restricted either to CD4+/CCR5+ or CD4+/CXCR4+ cells." (PMID 33207797, 2020). "Overall, the frequency of TBEV-specific CD4+ T cells was higher after vaccination than after infection." (PMID 32806696, 2020). "The FabA, whose CH1 alpha domain increases its affinity for the antigen, efficiently neutralizes CD4+T lymphocytes infection and HIV-1 transfer from LCs to autologous CD4+T cells, by different representative viral clades distributed worldwide." (PMID 33315937, 2020). "Examining IL-17A and IFN-γ in Foxp3-negative effector CD4+ T cells on day 3 after re-infection, we found that both sham groups had negligible but comparable levels of cytokine producers." (PMID 33240286, 2020). "In this context, the finding that infection induces CD4 helper responses targeting major structural proteins on the virus suggests that infection is capable of producing effective CD4 help for CD8 T cells and antibody responses." (PMID 32818217, 2020). "As a positive control, in one group of MFYcre mice, we intraperitoneally injected 1 x 106 CD4+CD25+GFP+ Tregs from wild-type (WT) Foxp3-GFP reporter mice or CD4+CD25+ Tregs from congenic CD45.1 mice 2 weeks prior to the infection." (PMID 33240286, 2020). "For patients coming in at the acute phase of infection, we are able to provide and analyze CD4+, CD8+ T-cells and HIV viral load evolution before, during and after CHIK infection." (PMID 32503031, 2020). "We have observed that TSPAN7 and actin nucleation were also involved in DC-mediated trans-infection of CD4+ T lymphocytes using transmitted/founder strains of HIV-1 (data not shown), which are CCR5-tropic and infect DCs more efficiently." (PMID 32181159, 2020). "The small intestines of naïve mice or mice 7 and 14 days post-infection with H. polygyrus were collected, LP leukocytes were isolated and CD4+ T cells subsequently analysed by flow cytometry." (PMID 31705860, 2020).
infection (continued). "The CD4+ T cell subset, tissue of origin, or the infection stage had at most slight effects on the initial integration site selection based on comparison to genomic and epigenetic annotations." (PMID 32970634, 2020). "Latently infected cells form a “viral reservoir” that is established early after infection with replication-competent proviruses integrated into the genomes of CD4 cells, with a substantial proportion in resting memory CD4 T cells." (PMID 33228686, 2020). "SIV induced a transient reduction in peripheral CD4 T cells that was most dramatic 3 weeks after infection, which coincided with peak viral RNA copies, as previously observed for this viral strain." (PMID 32730321, 2020). "In comparison with CD8+ T cells, the function of cross-reactive CD4+ T cells during sequential infection with heterotypic DENV serotypes or with DENV and ZIKV has been explored to a lesser extent." (PMID 31244855, 2019). "Two main mechanisms have been described for DC's role in viral dissemination: (i) cis-infection: The virus binds to the cell membrane molecules CD4 and CCR5, resulting in productive infection of DCs." (PMID 30787929, 2019). "Analysis of multifunctional CD4+ T cells is fundamental for characterizing the immune responses to vaccination or infection." (PMID 31649661, 2019). "For example, infection of pathogens through the nasal route supported polarization of naive CD4+ T cells into Th17 cells, whereas cutaneous, i.m., or i.v. infection supported Th1 polarization." (PMID 31356170, 2019). "Chemical inactivation of IgM reduced the neutralizing capacity of serum samples from anti-CD4-treated mice, indicating that this isotype was largely responsible for the neutralizing activity at day 7 after infection." (PMID 30677097, 2019). "Supernatant from co-culture assays are then assessed for the presence of p24 protein and Poisson statistics applied to estimate the frequency of resting cell infection that is reported as infectious unit per million CD4+ T cells (IUPM)." (PMID 31921056, 2019). "VacA-deficient bacteria colonized mice at significantly lower levels than the parental strain in both the neonatal and the adult infection model but showed similar levels of CD4+ T-cell infiltration overall." (PMID 30890606, 2019). "The lymphocyte-specific chemokine receptor CXCR3 expressed by activated T cells as well as NK cells is important for CD4+ Th1 cell migration to sites of inflammation and infection." (PMID 30915078, 2019). "Beyond the cytokine milieu, there are other parameters suggested to shape the CD4 T cell response to infection, including the impact of T cell receptor affinity and the epitope density that CD4 T cells encounter as they enter the antigen draining lymph node." (PMID 31134060, 2019). "For each primate CD4 tested, the median relative infection for all early HIV-1 Envs was significantly lower than macrophage-tropic Envs (P < 0.05; Mann–Whitney U test)." (PMID 31181085, 2019). "In these studies, we found that simultaneous stimulation of DCs with HIV-C and Chlamydia resulted in similar infection rates to CD4+ T cells as HIV-C-exposed iDCs." (PMID 31178863, 2019). "Following amplification, an increased frequency of CD4+ iNKT cells producing IL-4 was noticed in the group of patients free of infection compared with those who became infected and with healthy donors." (PMID 31253189, 2019). "First, infection of domestic cats with PLV prior to FIV exposure safeguards against the marked CD4+ T-cell depletion that is characteristic of FIV infection." (PMID 31500260, 2019). "Our results suggest a model in which signaling strength influences HIV-1 transcription and establishment of latency at the time of initial infection of CD4+ T cells." (PMID 31116788, 2019).
infection (continued). "Up to the best of our knowledge, the present study is the first to compare infection rates with intestinal parasites and T. gondii between HD patients and apparently healthy individuals in relation to CD4+ counts in Alexandria, Egypt." (PMID 31142275, 2019). "CD4+ effector/memory T cells (Tem) represent a leading edge of the adaptive immune system responsible for protecting the body from infection, cancer, and other damaging processes." (PMID 31120919, 2019). "Earlier studies indicated that human CD8 T-cells contribute to C. burnetii-specific IFNγ production, and in murine models CD8 T-cells appear to be more critical than CD4 T-cells for resolving infection." (PMID 30828331, 2019). "Depletion efficacy progressively increased from day 14, and by day 120 after infection only 7 out of 50 mice showed low residual levels of CD4+ T cells in lymph nodes and lung." (PMID 30949177, 2019). "In this system, the phenotypes seen in our previous infection assays were largely recapitulated despite the fact that this assay is virus-free and only requires three proteins (Env and CD4/CCR5)." (PMID 31181085, 2019). "The chemokine receptor CXCR3 expressed by activated T cells is important for trafficking of CD4+ Th1 cells to sites of inflammation and infection." (PMID 30915078, 2019). "HIV+ subjects had a mean duration of infection of 18.5 years and a mean nadir CD4+ T cell count of 186 cells/mL." (PMID 31297086, 2019). "At day 8 post infection, we still observed a largely decreased frequency of gp66-specific CD4+ T cells and polyclonal TFH cells in Tbx21−/− (ly5.2+) mice compared to control mice." (PMID 30984183, 2019). "We found that basolateral CM collected during the first 24 hr from epithelial cells and stromal fibroblasts is able to fully protect CD4+ T cells from infection." (PMID 30755713, 2019). "This trans infection to CD4+ T cells has also been seen using small intestine explants as well as primary rectal mononuclear cells." (PMID 31156637, 2019). "Flow cytometric analysis of the mesenteric lymph nodes revealed decreased CD4+ T cell frequency following infection with highly virulent group I strains." (PMID 30782062, 2019). "Median estimated infection day was 31 days and median CD4+ T-cell count and VL at the chemokine detection sampling point during PHI were 424 cells/μL and 78,500 copies/mL, respectively." (PMID 31836011, 2019). "On the other hand, and although also considered a susceptible model of VL, C57BL/6 mice never showed this IL-10 upregulation, while the resistant SV/129 mice showed an infection-induced IL-10 upregulation (in CD4+ T cells only) 8 weeks post-infection." (PMID 30881923, 2019). "It is thus important to integrate knowledge on myeloid cell functions with the kinetic of CD4 T cell priming and development in order to identify crucial molecules involved in these processes for a particular infection." (PMID 32038622, 2019). "Despite this decline, significant inhibition of infection by HIV of activated CD4+ T cells was observed in 4/4 experiments." (PMID 30755713, 2019). "This critical step of infection is driven by the HIV-1 envelope glycoprotein (Env) that sequentially binds to CD4 and coreceptors, CXCR4 or CCR5." (PMID 30691001, 2019). "In both groups combined, 57% of women were ART naïve, 21% had received ARVs for a previous pregnancy, and 22% were on ART for treatment of their infection (CD4 cell count <500 cells/ml)." (PMID 31142546, 2019). "Using a systemic mouse infection model we found that S. aureus reduced the numbers of splenic DC subsets, mainly CD4+ and CD8+ DCs independently of PSM secretion." (PMID 31134074, 2019). "For example, sequential infection or administration of different anti-flavivirus vaccines would recall cross-reactive memory T CD4+ and T CD8+ lymphocytes." (PMID 31616432, 2019). "We also determined if CXCR3 and T-bet are co-expressed on effector CD4+Foxp3− T cells and CD4+Foxp3+ Tregs during infection." (PMID 30915078, 2019).
infection (continued). "During chronic VL, the high expression of programmeded death protien-1 (PD-1) or Cytotoxic T-lymphocyte Antigen 4 (CTLA-4) causes unresponsiveness in CD4+ T-cell, which produce TGF-β in abundant levels and helps in persistence of infection." (PMID 31024534, 2019). "These cells were partially CD4+ and/or CXCR4+ before infection, and confirmed to be partially susceptible to HIV-1NL4−3 infection." (PMID 30761146, 2019). "Whereas, primary infection with S. flexneri induces differentiation of CD4+ cells to Th17 cells that produce IL-17A and IL-22, secondary infection also produces Th1 cells that secrete IFN-γ." (PMID 30800131, 2019). "Through the combined effects of IL-6 and TGF-β, CD4+ T cells differentiate into Th17 cells and secrete IL-17A, which plays a key role in host defense against infection." (PMID 31297140, 2019). "Factors related to infection with HPV oncogenic virus were a history of CD4 nadir < 200 cells/uL (OR: 2.363, 95% CI: 1.062–5.256), and simultaneous infection by low- and high-risk HPV genotypes (OR: 1.842; 95% CI: 1.015–3.344)." (PMID 31648254, 2019). "Both the HEV experimental infection and increased dietary Met content contributed to a significant (P < 0.001) decrease in the blood percentage of CD4+ cells, synthesizing IL-6 in response to mitogenic stimulation under in vitro conditions." (PMID 31675966, 2019). "During chronic or prolonged infections, many have observed the production of IL-21 by additional CD4+ T cell subsets including TFH and TH17 cells." (PMID 31379821, 2019). "Although several studies have reported that older age, smoking, worsened kidney function, low level of CD4+ T cells, glucocorticoid, and CYC therapy are significant predictors of severe infection, other predisposing factors remain unidentified." (PMID 31349802, 2019). "By contrast, all three signature genes are down-regulated in circulating CD4+ T cells of patients with latent tuberculosis infection when compared with those with active infection." (PMID 30753680, 2019). "In summary, these data definitively link the presence of microbial products in the circulation during acute/early infection with subsequent CD4+ T cell decline and cellular immune activation." (PMID 31449552, 2019). "HCV-infected individuals who cleared the infection in the acute phase demonstrated the presence of significant levels of HCV-specific CD4+ and CD8+ T cells." (PMID 31027278, 2019). "LCs from inner foreskin explant cultures and vaginal explant are not productively infected by HIV-1 but several studies suggest that these cells support trans-infection of CD4-positive T cells." (PMID 31354736, 2019). "In 35 pairs, one individual had a CD4 cell count above 800 cells per mm3 blood, indicative of being close to time of infection, while their partner was already immuno-compromised with a CD4 cell count below 400 cells per mm3 blood." (PMID 30926780, 2019). "Together with the previous experiments, this formally demonstrates that COXi treatment during Mtb aerosol infection can influence Th1 differentiation and/or effector-function of CD4 T cells and diminish their protective capacity." (PMID 31396568, 2019). "The CD4 TRM cells induced by natural infection or immunization with the wP vaccine secreted Th1- and Th17-type cytokines, especially IL-17." (PMID 30866771, 2019). "These four key findings show that the composition of the CD4 T cell response in the lungs after IAV varies over the course of infection, and has significant time-independent differences between C57BL/6 and BALB/c mice." (PMID 31632414, 2019). "There have been limited reports of memory CD4 + T cell inflation in MCMV, with evidence that CD4 + T cell responses directed to the m09 protein arise at later time points post-infection and are slightly inflationary." (PMID 30895366, 2019). "VCC formation was demonstrated to greatly facilitate trans-infection of HIV-1 from macrophages to autologous CD4+ T cells." (PMID 31178863, 2019).
infection (continued). "We have previously reported that LP-BM5 infection drives CD45hiCD11b+ macrophages as well as CD4+ and CD8+ T-cell neuroinflammation in the DRG of infected animals." (PMID 31354896, 2019). "The infection of target cells in the spleen leads to the influx of macrophages and CD4+ T cells in the white pulp, resulting in hyperplasia." (PMID 31675966, 2019). "This is consistent with the observations that it is mostly CD4 T lymphocytes that control an MHV-68 infection." (PMID 31736943, 2019). "Although the goal of each lab’s assay is the same—to quantify infectious provirus infecting resting CD4+ T cells—infection levels reported by UCSD were consistently higher than those reported by the other three labs." (PMID 30978183, 2019). "First, we found that the anti-CD35 antibody (10 μg/ml) alone was unable to block HIV trans-infection from CECs of CD4+ T cells." (PMID 31772057, 2019). "Inflammation also leads to increased recruitment of these activated target CD4+ T cells to the environment where infection occurs." (PMID 31396221, 2019). "We previously found that IAV-specific lung-resident memory CD4 T cells generated from naive TcR Tg donor cells displayed robust IL-2 production when assayed at day 30 post-infection and beyond." (PMID 31412088, 2019). "Transient depletion of CD8+ cells from vaccinated rats prolongs infection, while CD4+ cell depletion results in chronic viremia." (PMID 30846697, 2019). "In this project, we attempted to clarify some of the ambiguity of previous studies by focusing on a specific lymphocyte subset (CD4+ T cells) and utilizing a biological model of infection to assess exercise‐induced effects." (PMID 31552706, 2019). "Curiously, at this later time-point, the only infection-induced phenotype observed for C57BL/6 animals was the significant increase in the IL-2 production by splenic CD4+ T cells." (PMID 30881923, 2019). "γδ T cells have the capacity to serve as an early source of IL-17, and CD4 T cell differentiation begins to occur in the lymph nodes within the first few days of infection." (PMID 30908540, 2019). "Infection is assumed to occur at the end of the time step so that the expression, γTtexp(-Tt+Tt*K-β1Vt), gives the number of CD4+ T cells that survive infection per time step." (PMID 31532803, 2019). "The CD4+ T cell levels decrease during the first few days of the infection but later stabilize at normal levels." (PMID 31532803, 2019). "Remarkably, although LEDGIN was added during infection of the CD4+ T cells, submicromolar concentrations of the compound (0.5 μM) were sufficient to generate this phenotype." (PMID 30940165, 2019). "In one study, after infection with P. chabaudi NK cells promoted DC maturation in vitro, IL-12 production and ability to prime CD4 T cells to proliferate and produce IFNγ." (PMID 30873151, 2019). "To further investigate the mechanism of R5-tropic resistance in early infection, we next performed RNA-Seq to identify genes that were significantly up- or down-regulated in activated CD4 +T cells from ECr/VCr compared to Ctrl." (PMID 30964004, 2019). "Mitochondrial ROS (mROS) specifically has been shown to be able to act as a danger-associated molecular pattern (DAMP) and is known to direct the immune system by polarizing macrophages and differentiating CD4+ T cells during infection." (PMID 31412915, 2019). "APC from HIV seronegative donors treated with ART in vitro (CCR5 agonist, NRTI, PI and NNRTI, alone or in combination), were loaded with HIV R5-tropic HIVBal and mixed with autologous or heterologous CD4+ T lymphocytes to assess trans infection." (PMID 31304185, 2019). "This method can be applied to better understand the complex functional profile of CD4+ T-cell responses upon vaccination or infection." (PMID 31649661, 2019). "Clustering of genetically similar viruses is influenced by time since infection when patients are sampled, which is confounded by patients' age as well as CD4 and clinical stage of infection." (PMID 31280593, 2019).